PRAC1 (PRAC1 small nuclear protein)
Synonyms: C17orf92; PRAC
Tractability: No criterion of Open Targets' tractability assessment is met for any kind of drug.
Gene: Protein-coding gene on chromosome 17 (48,721,719 to 48,723,082, reverse strand). Ensembl gene ENSG00000159182.
Subcellular location: Nucleus
Subcellular location (Human Protein Atlas): Nucleoplasm; Cytosol
Gene Ontology:
Cellular component: nucleoplasm; nucleus
Genetic constraint (gnomAD): Loss-of-function variants: 6 observed, 5.46 expected, observed/expected ratio (o/e) 1.1, 90% interval 0.59 to 1.84. That is too few expected variants to judge how well the gene tolerates losing a copy. Missense variants: 72 observed, 67.46 expected, observed/expected ratio (o/e) 1.07, 90% interval 0.88 to 1.3. Synonymous variants: 32 observed, 27.46 expected, observed/expected ratio (o/e) 1.17, 90% interval 0.88 to 1.56.
Homologues: Orthologues: chimpanzee PRAC1 (98% identical), macaque PRAC1 (81% identical).
Diseases named in the same sentence as PRAC1 in open-access papers:
PRAC1 is named in the same sentence as 15 diseases in open-access papers, as found by Europe PMC text mining. Sharing a sentence is not in itself a finding about the gene and the disease. The quoted sentences say what the papers report.
prostate carcinoma (8 papers, 2005 to 2023). A carcinoma that arises from epithelial cells of the prostate gland. "Genes that are of high importance in our RF models that are associated with both LCC and prostate cancer include PRAC1, HOXB13, SPAG16." (PMID 37434131, 2023). "Instead, it is previously identified as prostate cancer susceptibility genes PRAC1 and PRAC2, specifically over-expressed in human prostate and colon cancer." (PMID 34941772, 2021). "PRAC1 has been previously associated with LCC as well as prostate cancer." (PMID 37434131, 2023).
colon cancer (3 papers, 2018 to 2021). "However, the function of PRAC1 in colon cancers remains elusive." (PMID 33076847, 2020).
colorectal cancer (2 papers, 2018 to 2025). A primary or metastatic malignant neoplasm that affects the colon or rectum. "In left-sided colorectal cancer, PRAC1 emerged as the highest-scoring gene with a DynaFIC score of 100.00, despite marked differential expression (log2FC = −3.78)." (PMID 41155316, 2025).
polycystic ovary (1 paper, 2014). "Our results suggested that expression of Rac1, pRac1 and its activity were significantly reduced in the hyperandrogenized ovary with DHEA (polycystic ovary)." (PMID 24628852, 2014).
cancer (6 papers, 2015 to 2025). A tumor composed of atypical neoplastic, often pleomorphic cells that invade other tissues. "Of the 15 significant features in our gene-only dataset, the highest importance score was for the Prostate Cancer Susceptibility Candidate 1 (PRAC1) gene, which has higher expression in LCC." (PMID 37434131, 2023). "Prostate Cancer Susceptibility Candidate Protein 1(PRAC1) is highly expressed in the prostate." (PMID 39988626, 2025). "Since no studies to date have shown an association between miR-320a, PKCγ and pRac1 in normal epidermal homeostasis or wound healing, our findings on the ΔNp63α/miR320a/PKCγ/pRac1 axis are novel and suggest a role in both cancer cells as well as normal keratinocyte homeostasis and/or wound healing." (PMID 31515469, 2019).
PRAC1 also shares sentences with these, for which no sentence is quoted: tumor (5 papers); Chagas disease (2); infection (2); autoimmune liver diseases (1); bladder cancer (1); bladder tumors (1); colonic dysplasia (1); injury (1); osteoporosis (1); renal cell carcinoma (1).